TNFRSF10B (TNF receptor superfamily member 10b)
Description:
Receptor for the cytotoxic ligand TNFSF10/TRAIL. The adapter molecule FADD recruits caspase-8 to the activated receptor. The resulting death-inducing signaling complex (DISC) performs caspase-8 proteolytic activation which initiates the subsequent cascade of caspases (aspartate-specific cysteine proteases) mediating apoptosis. Promotes the activation of NF-kappa-B. Essential for ER stress-induced apoptosis.
Synonyms: TRAIL-R2; CD262; DR5; KILLER; TRAILR2; TRICK2; ZTNFR9; TRICK2A; TRICKB; KILLER/DR5; TRICK2B
Tractability: Antibody: a drug acting on it is in phase 2 or 3 trials; its Gene Ontology location is reachable by antibodies, with high confidence; UniProt predicts a signal peptide or a membrane-spanning region. PROTAC: ubiquitination databases record sites on it. Other modalities: a drug acting on it is in phase 2 or 3 trials.
Target class: Membrane receptor
Gene: Protein-coding gene on chromosome 8 (23,020,133 to 23,069,071, reverse strand). Ensembl gene ENSG00000120889.
Subcellular location: Membrane
Pathways (Reactome):
Programmed Cell Death: CASP8 activity is inhibited; Caspase activation via Death Receptors in the presence of ligand; Dimerization of procaspase-8; RIPK1-mediated regulated necrosis; Regulation by c-FLIP
Hemostasis: Cell surface interactions at the vascular wall
Signal Transduction: TRAIL signaling
Gene Ontology:
Molecular function: protein binding; TRAIL receptor activity; signaling receptor activity; TRAIL binding; death receptor activity
Biological process: cellular response to mechanical stimulus; defense response to tumor cell; intrinsic apoptotic signaling pathway in response to endoplasmic reticulum stress; positive regulation of canonical NF-kappaB signal transduction; response to endoplasmic reticulum stress; TRAIL-activated apoptotic signaling pathway; activation of NF-kappaB-inducing kinase activity; apoptotic process; cell surface receptor signaling pathway; extrinsic apoptotic signaling pathway via death domain receptors; positive regulation of apoptotic process; regulation of apoptotic process; signal transduction
Cellular component: cell surface; plasma membrane; membrane
Genetic constraint (gnomAD): Loss-of-function variants: 34 observed, 42.06 expected, observed/expected ratio (o/e) 0.81, 90% interval 0.61 to 1.08. The upper end of that interval is the gene's LOEUF score, 1.08, which puts it in group 4 of 6, group 1 being the genes least tolerant of losing a copy. Missense variants: 583 observed, 577.65 expected, observed/expected ratio (o/e) 1.01, 90% interval 0.94 to 1.08. Synonymous variants: 230 observed, 224.74 expected, observed/expected ratio (o/e) 1.02, 90% interval 0.92 to 1.14.
Homologues: Orthologues: chimpanzee TNFRSF10B (97% identical), macaque TNFRSF10B (78% identical), zebrafish nradd (14% identical), tropical clawed frog tnfrsf10b (13% identical), tropical clawed frog nradd (12% identical), zebrafish tnfrsfa (12% identical), zebrafish tnfrsf11a (11% identical), zebrafish hdr (10% identical), zebrafish tnfrsf1b (10% identical), zebrafish cd40 (10% identical), mouse Tnfrsf22 (8% identical), rat Tnfrsf22 (8% identical), and 3 more. Paralogues in human: TNFRSF10A (52% identical), TNFRSF10D (42% identical), TNFRSF10C (21% identical), TNFRSF1A (15% identical), TNFRSF25 (14% identical), TNFRSF11A (13% identical), NGFR (13% identical), LTBR (13% identical), TNFRSF21 (13% identical), FAS (12% identical), TNFRSF1B (11% identical), RELT (10% identical), and 9 more.
Diseases named in the same sentence as TNFRSF10B in open-access papers:
TNFRSF10B is named in the same sentence as 230 diseases in open-access papers, as found by Europe PMC text mining. Sharing a sentence is not in itself a finding about the gene and the disease. The quoted sentences say what the papers report.
breast carcinoma (125 papers, 2005 to 2026). "We show that miR-519a-3p indeed leads to inhibition of TRAIL- and FasL-induced apoptosis in breast cancer cell lines by directly targeting the proapoptotic TNFRSF10B (TRAIL-R2) and CASP8 (caspase-8) mRNAs." (PMID 28771222, 2017). "Our findings are corroborated by breast cancer patient data, showing that high expression of miRNA-519a-3p and low coexpression of the target genes CASP7, CASP8 and TNFRSF10B correlate with poor relapse-free survival in breast cancer patients." (PMID 28771222, 2017). "Here, we analyzed the impact of the expression of direct and indirect miR-519a-3p target genes CASP8, TNFRSF10B and CASP-7 on the clinical outcome using published breast cancer data sets." (PMID 28771222, 2017). "The TNFRSF10b/DR5 receptor regulates radiation-induced apoptosis in mice and in breast cancer cell lines." (PMID 26982083, 2016). "However, the apoptosis-related genes TRAIL-R2 (TNFRSF10B) and caspase-8 (CASP8] are targeted and inhibited by the oncogenic miR-519a-3p, which is highly expressed in breast cancer." (PMID 41614928, 2026). "Notably, TNFRSF10B, GSTP1, and PDIA3 were found to interact with the target proteins of current medications used in prostate or breast cancer treatment." (PMID 37735436, 2023).
colon carcinoma (107 papers, 2003 to 2026).
lung carcinoma (70 papers, 2007 to 2026). "Collectively, these data reveal that the mRNA expression of YIPF2 and TNFRSF10B is associated with malignant progression in lung cancer patients." (PMID 32303681, 2020). "DDIT3 cooperates with KAT2A to up-regulate TNFRSF10A and TNFRSF10B expressions and to induce the endoplasmic reticulum stress-mediated apoptosis in lung cancer." (PMID 27931220, 2016). "Finally, YIPF2 expression tended to be positively associated with the expression of TNFRSF10B in two GEO datasets (GDS1688 and GDS3627), which contained 29 lung cancer cell lines and 58 NSCLC cell lines respectively." (PMID 32303681, 2020). "Several previous studies reported the prognostic value of a single immune-related gene in EPC or lung cancer, such as FGFR1, TNFRSF10B, and IL1B." (PMID 36147506, 2022). "Decreased expression of genes, such as TNFRSF10B, MIA2, and BBC3, are answerable for the progression of various cancers, such as lung cancer, hepatocellular carcinoma, head, and neck cancer, but low expression of these genes may be responsible for the development of BRCA." (PMID 31311202, 2019).
prostate carcinoma (64 papers, 2007 to 2025). A carcinoma that arises from epithelial cells of the prostate gland. "Our study indicatied that genetically predicted KDELC2 (OR: 0.89, 95% CI 0.86–0.93) and TNFRSF10B (OR: 0.74, 95% CI 0.65–0.83) are inversely associated with prostate cancer." (PMID 37735436, 2023). "Further, TNFRSF10B expression is lower in higher grade prostate tumours and a recent study of PARP inhibitors in prostate cancer cell lines suggested that TNFRSF10B may provide a mechanism by which the cancer drug olaparib induces apoptosis." (PMID 38878676, 2024). "Interestingly, TNFSF10 was also downregulated and TNFRSF10B (DR5) was increased in AT2R-mediated apoptosis in prostate cancer cells in our previous study." (PMID 28599664, 2017). "Therefore, TNFRSF10B also shows promise as a target for prostate cancer." (PMID 37735436, 2023). "The apparent protective association we observe with prostate cancer risk is in line with the results from multiple phase I/II trials of TNFRSF10B agonists that support their use for the treatment of multiple cancer endpoints, though not yet including prostate cancer." (PMID 38878676, 2024).
colorectal cancer (60 papers, 2005 to 2026). A primary or metastatic malignant neoplasm that affects the colon or rectum. "In Affymetrix primeview human GeneChip array, we found six upregulated genes (STAT1, ATF2, TNFRSF10B, TGFBR2, BAX, and SQSTM1) and two downregulated genes (SLC4A7 and CD274) related to apoptosis and proliferation of colorectal cancer cells after hsa_circ_0064559 knockdown." (PMID 37280630, 2023).
melanoma (59 papers, 2006 to 2025). A malignant, usually aggressive tumor composed of atypical, neoplastic melanocytes. "TNFRSF10B was associated with a lower risk of both kidney cancer [OR: 0.73, 95% CI: 0.64 to 0.83; PP4: 0.99] and non-malignant melanoma." (PMID 38684708, 2024).
pancreatic cancer (56 papers, 2003 to 2025). "This pro-survival effect of HuR in pancreatic cancer cells was observed in several other studies, and additional HuR target genes like YAP1 and DR5/TNFRSF10B as well as their associated pathways have been shown to be activated or inhibited by HuR." (PMID 40427100, 2025).
hepatocellular carcinoma (43 papers, 2010 to 2025). A malignant tumor that arises from hepatocytes. "Specifically, loss of TNFRSF10B expression is a frequent event in hepatocellular carcinoma (HCC) and lung and testicular cancers." (PMID 32316112, 2020).
ovarian carcinoma (39 papers, 2011 to 2025). A malignant neoplasm originating from the surface ovarian epithelium. "Our results showed that high expression of DR5 (TNFRSF10B) was significantly associated with improved overall survival in patients with ovarian cancer (n = 278, HR: 0.65, Cox p-value: 0.027138)." (PMID 29973205, 2018). "Terminal node 1 was defined as individuals carrying the homozygous variant genotypes (VV) for rs11152377 of BCL-2, following by the homozygous wildtype (WW) for rs2889 of TNFRSF10B, which had the lowest ovarian cancer risk as the reference node." (PMID 27462919, 2016).
gastric cancer (29 papers, 2012 to 2026). A primary or metastatic malignant neoplasm involving the stomach. "In this study we found that the expression of DR5 (TRAILR2, TNFRSF10B) presented a malignant phenotype as an independent risk factor for poor prognosis in gastric cancer patients, which was different from DR4 (TRAILR1, TNFRSF10A)." (PMID 37879960, 2023).
leukemia (28 papers, 2006 to 2024). A malignant (clonal) hematologic disorder, involving hematopoietic stem cells and characterized by the presence of primitive or atypical myeloid or lymphoid cells in the bone marrow and the blood. "Test compounds induced apoptosis in chronic myelogenous (K562) and acute lymphoblastic (MOLT-4) leukemia cells by activation of receptor and mitochondrial apoptotic pathways and increased the expression of proapoptotic genes (BAX, NOXA, HTRA2, TNFRSF10B, ESRRBL1)." (PMID 31487824, 2019). "Notably, leukemia cells with a reduced expression of death receptor genes (Fas associated via death domain (FADD), BH3 interacting domain death agonist (BID), caspase 8 (CASP8), TNF receptor superfamily member 10b (TNFRSF10B)) have been associated with patients showing no response." (PMID 38397092, 2024).
non-small cell lung carcinoma (27 papers, 2007 to 2025). A group of at least three distinct histological types of lung cancer, including non-small cell squamous cell carcinoma, adenocarcinoma, and large cell carcinoma. "Polymorphisms and haplotypes in TNFRSF10B are associated with an increased risk of death in non-small cell lung cancer." (PMID 37372463, 2023).
bladder cancer (11 papers, 2013 to 2025). "The expression of TNFRSF10A and TNFRSF10B was further enhanced by combinatorial treatment, suggesting that apoptosis‐related genes were involved in the regulation of proliferation of bladder cancer cells with melatonin and/or VPA." (PMID 28593135, 2017).
breast tumor (9 papers, 2010 to 2024). "WA inhibits breast tumor growth by upregulation of death receptor 5 (DR5, also known as TRAIL-R2/TRICK-2/KILLER/TNFRSF10B)." (PMID 39057095, 2024).
neuroblastoma (8 papers, 2008 to 2023). Neuroblastoma (NB) is the most common solid, extracranial childhood tumor. "Although most human neuroblastoma cells exhibit drug resistance because of their low levels of caspase-8 expression, previous reports have shown that TRAIL-receptor 2 (TRAIL-R2/DR5/TNFRSF10b) is an important upstream effector of caspase-8." (PMID 29113358, 2017).
atherosclerosis (6 papers, 2015 to 2025). A disease characterized by the build-up of fatty material and calcium deposition in the arterial wall resulting in partial or complete occlusion of the arterial lumen. "Moreover, tRF-60:76-Val-AAC-1-M5 might target Tnfrsf10b and Bcl2l1 to influence this therapeutic heterogeneity through the lipid and atherosclerosis signaling pathway." (PMID 36247465, 2022). "Moreover, tRF-60:76-Val-AAC-1-M5 might target Tnfrsf10b and Bcl2l1 to influence the observed therapeutic heterogeneity through the lipid and atherosclerosis signaling pathways." (PMID 36247465, 2022). "In this study, our group used unmodified tRF fragments for overexpression research and confirmed that tRF-60:76-Val-AAC-1-M5 might target Tnfrsf10b and Bcl2l1 to influence the therapeutic heterogeneity of sacubitril/valsartan through the lipid and atherosclerosis signaling pathway." (PMID 36247465, 2022). "A total of 6 genes were enriched in the lipid and atherosclerosis signaling pathway (CAMK2B, VAV3, PLCB3, NFATC3, TNFRSF10B, and BCL2L1), and these genes were regulated by tRF-60:76-Val-AAC-1-M5." (PMID 36247465, 2022).
heart failure (6 papers, 2017 to 2023). Inability of the heart to pump blood at an adequate rate to meet tissue metabolic requirements. "Recently, death receptor (DR; also called TRAIL-R2, TNFRSF10B) 5 and its ligand, TNF-Related Apoptosis-Inducing Ligand (TRAIL; also called Tnfsf10, APO2L, and CD253), have been linked to multiple forms of human heart failure, although the function of DR5 in the heart is poorly understood." (PMID 34527710, 2021).
Hyperglycemia (6 papers, 2018 to 2026). An increased concentration of glucose in the blood. "In vitro, hyperglycemia induced transient upregulation of activin A and TNFRSF10B at 24 h, followed by a decline at 48 and 72 h." (PMID 41463007, 2025). "Our in vitro studies revealed increased gene and protein expression with hyperglycemia, and these findings are in line with previous reports of increased TNFRSF10B expression with hyperglycemia." (PMID 41463007, 2025). "Immunofluorescence staining of the fibroblasts treated with hyperglycemia showed increased fluorescence intensity compared to cells cultured in normal medium for both activin A and TNFRSF10B at 24 hrs." (PMID 41463007, 2025).
lung adenocarcinoma (6 papers, 2018 to 2023). A carcinoma that arises from the lung and is characterized by the presence of malignant glandular epithelial cells. "Similarly, mRNA expression of TNFRSF10B was also lower in lung adenocarcinoma tissues than that in normal tissues in two Oncomine datasets (TCGA Lung 2 and Bhattacharjee Lung)." (PMID 32303681, 2020). "Similarly, our mRNA expression signature in EGFR-mutated tumors included DUSP4, EGFR, TNFRSF10B, and LRRC3, all reportedly deregulated in EGFR-mutated lung adenocarcinoma." (PMID 30404194, 2018).
COVID-19 (5 papers, 2021 to 2025). A disease caused by infection with severe acute respiratory syndrome coronavirus 2. "IL22RA1 has been identified as a crucial gene for critical COVID-19 and as a significant pathway involving viral protein interactions with cytokines, cytokine receptors such as IL22RA1 and TNFRSF10B, and cytokine–cytokine receptor interactions." (PMID 40362649, 2025). "The common plasma proteins that were higher in the COVID-19 patients than controls and that were higher in the late recovery group than the early recovery group for phases 1 and 2 were WFDC2, CHI3L1, GDF15, KRT19, and TNFRSF10B." (PMID 36331721, 2023).
liver disease (5 papers, 2009 to 2026). "Hepatocyte death is a central event during liver disease progression, in which immune cells play key roles by activating members of the Tumor Necrosis Factor Receptor Superfamily (TNFRSF), including TNFR1 (TNFRSF1A), Fas (TNFRSF6) and TRAIL-R2 (TNFRSF10B)." (PMID 28835677, 2017).
Alzheimer disease (4 papers, 2021 to 2024). A progressive, neurodegenerative disease characterized by loss of function and death of nerve cells in several areas of the brain leading to loss of cognitive function such as memory and language. "Further analysis of TNFRSF10B, a key gene in the risk model, indicated that it is strongly associated with immune and metabolic pathways, as well as with the regulation of Alzheimer’s disease-related pathways." (PMID 39650656, 2024). "A similar pattern has been shown in other pathological situations such as in the advanced stage of Alzheimer’s disease, where TNFSF10 secreted by astrocytes binds to TNFRSF10B on neurons and triggers caspase-8-dependent apoptosis." (PMID 34835061, 2021). "Similarly, in our study utilizing KEGG gene sets, we found that oxidative phosphorylation, citrate cycle (TCA cycle), Alzheimer’s disease, and selenoamino acid metabolism were inhibited in the high expression groups of RHBDF2 and TNFRSF10B." (PMID 38915415, 2024).
Ewing sarcoma (4 papers, 2021 to 2024). A small round cell tumor that lacks morphologic, immunohistochemical, and electron microscopic evidence of neuroectodermal differentiation. "Several of these Ewing sarcoma tumor cell–expressed genes have been previously studied in Ewing sarcoma [AXL, WNT5A, IGF-1R, TNFRSF10B (TRIAL-R2/DR5)], and have been described as potential targets in Ewing sarcoma and/or to be involved in Ewing sarcoma tumor cell migration/metastatic potential." (PMID 37823774, 2023).
testicular cancer (4 papers, 2016 to 2020). A primary or metastatic malignant neoplasm that affects the testis. "In follow-up studies, this group used 3’ RACE to detect more genes controlled by LTR12s in primary human testis and in the GH testicular cancer cell line and reported hundreds of transcripts, including an isoform of TNFRSF10B which encodes the death receptor DR5." (PMID 27980689, 2016). "However, treatment with inhibitors of histone deacetylases has been shown to reverse the epigenetic repression of the ERV9 LTR promoters, leading to induction of TP63 and TNFRSF10B transcription and ultimately promoting apoptosis of testicular cancer cells." (PMID 28893944, 2017). "Importantly, the TP63 (tumour protein p63) and TNFRSF10B (TNF receptor superfamily member 10b) genes are suppressed in primary human testicular cancer cells or cell lines, likely permitting tumour growth." (PMID 28893944, 2017). "Functionally, this enhanced LTR12 promoter activity resulted in elevated levels of the TNFRSF10B gene product, death receptor 5 (DR5), and testicular cancer cell death." (PMID 27172897, 2016).
thyroid cancer (4 papers, 2019 to 2025). "The results showed that eight key genes (NUAK2, TNFRSF10B, TNFRSF10C, TNFRSF12A, UNC5B, and PMAIP1) exhibited good diagnostic performance in differentiating between thyroid cancer patients and controls." (PMID 39104814, 2024). "The receptor TNFRSF10B could cause degradation via ubiquitination and trigger the transcription factor GATA1, and its mutation can enhance the suppression of apoptosis in thyroid cancer cells to promote the selective growth of cancer cells." (PMID 31126066, 2019). "Given that TNFRSF10B, TNFRSF10C and TNFRSF12A are up-regulated in thyroid cancer tissues and correlate with macrophages." (PMID 39104814, 2024). "TNFRSF10B, TNFRSF10C, TNFRSF12A, UNC5B, PMAIP1, and IL18 had increased expression in thyroid cancer tissues, while NUAK2 was decreased." (PMID 39104814, 2024).
mesothelioma (3 papers, 2021 to 2022). A usually malignant and aggressive neoplasm of the mesothelium which is often associated with exposure to asbestos. "To validate the most significant genes identified across both models as conferring resistance to rTRAIL, we used synthetic crRNA to knock out expression of FADD, BID, CASP8, and TNFRSF10B (TRAIL-R2) in the rTRAIL-sensitive MSTO-211H mesothelioma cell line stably expressing Cas9." (PMID 35086954, 2022). "The same effects on MEDI3039 sensitivity were detected in analogous TNFRSF10B, FADD, CASP8, and BID cRNA KO models derived from two additional rTRAlL-sensitive mesothelioma cell lines H2804 and NCI-H28." (PMID 35086954, 2022).